LCAL1 (lung cancer associated lncRNA 1)
Synonyms: onco-lncRNA-27
Gene: Long non-coding RNA gene on chromosome 6 (79,269,761 to 79,313,395, reverse strand). Ensembl gene ENSG00000286042.
Diseases named in the same sentence as LCAL1 in open-access papers:
LCAL1 is named in the same sentence as 9 diseases in open-access papers, as found by Europe PMC text mining. Sharing a sentence is not in itself a finding about the gene and the disease. The quoted sentences say what the papers report.
lung carcinoma (6 papers, 2014 to 2025). "Functional validation shows that the largest differentially expressed lncRNA in lung cancer, LCAL1 (lung cancer-associated lncRNA 1), contributes to tumor cell proliferation." (PMID 33627711, 2021). "Furthermore, it was reported that lung cancer-associated lncRNA 1 (LCAL1) was overexpressed in lung cancer tissues, which suppressed autophagic cell death, supporting cancer cell survival and proliferation by deactivating the AMPK/ULK1 signalling pathway." (PMID 35379783, 2022). "LCAL1 has been identified as a key regulator in lung cancer, where it supports tumor growth by inhibiting AMPK-related antitumor pathways." (PMID 40724881, 2025). "LCAL1, a newly discovered long noncoding RNA associated with lung cancer, has not yet been extensively studied; our findings indicate that its high expression correlates with improved prognosis in lung adenocarcinoma patients, in line with previous reports." (PMID 40672941, 2025). "Cellular proliferation studies revealed an oncogenic phenotype, as shown by siRNA knockdown studies of LCAL1 resulting in decreased cellular growth in two cellular models of lung cancer, a non-small cell lung carcinoma cell line (H322M) and a squamous cell carcinoma cell line (HCC95)." (PMID 25116943, 2014). "Overexpression of LCAL1 in normal BEAS-2B cells, at physiological levels in human tumors, is proof of principle that this lncRNA is sufficient to affect cellular growth independently of other common cancer mutations, thus highlighting the importance of LCAL1 in lung cancer biology." (PMID 25116943, 2014). "In addition, it was also found that lung cancer-related lncRNA1 (LCAL1) can induce aerobic glycolysis of lung cancer cells through the AMPK/HIF-1α axis and promote the rapid proliferation of lung cancer cells." (PMID 36124026, 2022).
esophageal squamous cell carcinoma (1 paper, 2025). Esophageal squamous cell carcinoma (ESCC) is a type of esophageal carcinoma (EC) that can affect any part of the esophagus, but is usually located in the upper or middle third. "Moreover, LCAL1 forms part of an autophagy-related lncRNA prognostic signature in esophageal squamous cell carcinoma, underlining its broader relevance across cancers." (PMID 40724881, 2025).
lung adenocarcinoma (1 paper, 2025). A carcinoma that arises from the lung and is characterized by the presence of malignant glandular epithelial cells. "Given that LCAL1 and RHOV have been previously reported as prognostic genes, we validated the novel prognostic gene MARCHF4 via qRT-PCR, demonstrating that its expression was significantly upregulated in lung adenocarcinoma cells compared to normal lung epithelial cells." (PMID 40672941, 2025).
lung disease (1 paper, 2014). "To determine the importance of these LCALs in lung disease pathology, we proceeded with functional studies of LCAL1, the top up-regulated lncRNA in both LUAD and LUSC." (PMID 25116943, 2014).
squamous cell carcinoma (1 paper, 2014). A carcinoma arising from squamous epithelial cells. "In our original panel of nine different cancer cell lines, LCAL1 was only highly differentially expressed in one cell line; therefore, we screened additional squamous cell carcinoma lines and found LCAL1 to be highly differentially expressed in HCC95." (PMID 25116943, 2014). "To determine if the lncRNAs found in this study have phenotypic consequences, we chose to examine the most differentially expressed lncRNA, LCAL1, in both adenocarcinoma and squamous cell carcinoma." (PMID 25116943, 2014).
adenocarcinoma (1 paper, 2014). A common cancer characterized by the presence of malignant glandular cells. "Greater than 50% knockdown of LCAL1 in the cell line H322M, which models adenocarcinoma, with two different siRNAs resulted in decreased cell growth as measured by cell counting for six days." (PMID 25116943, 2014).
LCAL1 also shares sentences with these, for which no sentence is quoted: cancer (3 papers); tumor (2); non-small cell lung carcinoma (1).